NRIP1 (nuclear receptor interacting protein 1)
Diseases named in the same sentence as NRIP1 in open-access papers (continued):
Sharing a sentence is not in itself a finding about the gene and the disease.
breast tumor (5 papers, 2004 to 2022). "The elevated NRIP1 levels in cancer cell lines and tumor samples, as well as the induction of apoptosis by siNRIP1 in vitro, suggested that the depletion of NRIP1 might suppress the breast tumors in vivo." (PMID 26492163, 2015). "That NRIP1 transcript levels were elevated in ER+ compared to ER- breast tumors suggests that the downstream function of other nuclear hormone receptor may be coordinately modulated by elements of the ER transcriptional cascade." (PMID 15345050, 2004).
diabetes (5 papers, 2016 to 2022). "A previous study has reported that NRIP1 expression is higher in diabetes patients and correlates with inflammatory cytokines in plasma and peripheral blood mononuclear cells (PBMCs)." (PMID 26799933, 2016).
cardiac hypertrophy (4 papers, 2011 to 2025). "Both striated and cardiac-specific Nrip1 mouse lines exhibited mild cardiac hypertrophy at baseline with normal function and an absence of histologic or gene markers of pathologic growth." (PMID 36927960, 2023).
cervical cancer (4 papers, 2017 to 2023). A primary or metastatic malignant neoplasm involving the cervix. "NRIP1 was demonstrated as an independent predictor of poor survival for cervical cancer patients." (PMID 32653032, 2020).
Down syndrome (4 papers, 2017 to 2022). "NRIP1 protein levels are considerably increased in the hippocampus from Down Syndrome patients." (PMID 28848387, 2017). "Furthermore, the NRIP1-PGC-1α axis might represent a potential therapeutic target for restoring altered mitochondrial function in the Down’s syndrome." (PMID 28218651, 2017).
leukemia (4 papers, 2010 to 2023). A malignant (clonal) hematologic disorder, involving hematopoietic stem cells and characterized by the presence of primitive or atypical myeloid or lymphoid cells in the bone marrow and the blood. "For example, transcription factors Dot1l and Nrip1 which are part of the ‘early-maintained’ response have been implicated in mixed lineage leukaemia and acute lympoblastic leukaemia respectively." (PMID 26415229, 2015). "Nrip1 and Rex3 were proposed to be diagnostic markers of different forms of leukemias." (PMID 20098702, 2010). "Altogether, these data suggest that the NRIP1 gene could be involved in the pathogenesis of different types of leukemia." (PMID 25879677, 2015). "RNA sequencing (RNA-seq) of leukemia cells revealed the presence of a novel NRIP1::PDGFRB fusion gene, where an untranslated region of NRIP1 intron 3 was connected to exons 12–23 of PDGFRB." (PMID 38071343, 2023).
psoriasis (4 papers, 2016 to 2021). An autoimmune condition characterized by red, well-delineated plaques with silvery scales that are usually on the extensor surfaces and scalp. "Moreover, our recent studies reported that metabolic-associated genes PCSK9 and nuclear receptor interacting protein 1 (NRIP1) both play important roles in psoriasis via the NFκB pathway." (PMID 31824416, 2019). "Importantly, together, PCSK9 and NRIP1 may be two potential therapeutic targets for both psoriasis and metabolic syndrome by regulating the NFκB-associated chronic inflammatory status." (PMID 31824416, 2019). "Expression of NRIP1 and p65 were also significantly elevated in PBMCs of psoriasis patients compared to healthy controls (1.4860 ± 0.1408 vs. 1.0110 ± 0.05578, P= 0.0165 & 2.2220 ± 0.4975 vs. 1.019 ± 0.08736, P= 0.0385, respectively." (PMID 27708240, 2016). "In order to investigate its potential role in psoriasis, we first measured the expression of NRIP1 in the skin lesions and PBMCs of psoriasis patients." (PMID 27708240, 2016). "Our data firstly showed that NRIP1 mRNA was increased in PBMCs of psoriasis patients compared to healthy controls." (PMID 27708240, 2016). "In the current study, we investigated the role of NRIP1 in the pathogenesis of psoriasis, including cell proliferation, apoptosis and inflammation." (PMID 27708240, 2016). "The aim of this study is to investigate the expression of NRIP1 and to explore its roles in the pathogenesis of psoriasis." (PMID 27708240, 2016). "Our laboratory revealed that suppression of NRIP1 in CD4+ T cells that were isolated from psoriasis patients could downregulate the expression of RelA/p65 and decrease the secretion of IL-17, thus inhibiting the inflammation in psoriasis." (PMID 31824416, 2019). "In this study, suppression of NRIP1 in CD4+ T cells also decreased the secretion of IL-17 significantly, suggesting that NRIP1 may involve in psoriasis via upregulating IL-17." (PMID 27708240, 2016). "However, more detailed studies are needed to confirm the mechanism behind the function of NRIP1 on inflammation and cell growth and to explore its other potential roles in psoriasis." (PMID 27708240, 2016). "Our results suggest that NRIP1 may play a role in the pathogenesis of psoriasis and may be a novel therapeutic target for psoriasis." (PMID 27708240, 2016). "qRT-PCR analyses found that both NRIP1 and RelA/p65 were elevated in psoriatic lesions compared to psoriatic non-lesions and normal controls, and also overexpressed in peripheral blood mononuclear cell (PBMCs) of psoriasis patients." (PMID 27708240, 2016). "In conclusion, our data suggests that NRIP1 is overexpressed both in skin and PBMCs of psoriasis patients and may be involved in the abnormal proliferation and apoptosis of keratinocytes, as well as the immune reaction through the regulation of RelA/p65." (PMID 27708240, 2016). "Overexpression of NRIP1 in the tissues of patients and the effects of silencing NRIP1 in HaCaT cells strongly suggested that the depletion of NRIP1 may improve the skin lesion of psoriasis." (PMID 27708240, 2016). "NRIP1 was found to modulate the transcription and secretion of pro-inflammatory cytokines by activating NF-κB and this mechanism could also be found in autoimmune disease like psoriasis." (PMID 34615554, 2021). "To investigate the function of NRIP1 in regulating the secretary profile of CD4+ T cells, we isolated CD4+ T cells from psoriasis patients and used siRNA to silence NRIP1 (siNRIP1) expression." (PMID 27708240, 2016). "Therefore, NRIP1 may be a potential therapeutic target for psoriasis." (PMID 27708240, 2016). "Nuclear receptor interacting protein 1 (NRIP1), a co-regulator for numerous nuclear receptors, was found to be overexpressed in psoriatic lesions and in peripheral blood mononuclear cells of patients with psoriasis." (PMID 30744173, 2019).
psoriasis (continued). "Suppression of NRIP1 in HaCaT cells could significantly inhibit cell growth and induce apoptosis, and the suppression of NRIP1 in CD4+ T cells isolated from psoriasis patients could downregulate the expression of RelA/p65 and decrease the secretion of IL-17." (PMID 27708240, 2016). "A recent study revealed that NRIP1 may stimulate the activity of NF-κB by forming a trimeric complex with RelA and CBP, and upregulate downstream inflammatory genes, including TNF-α and IL-6, both of which play crucial roles in the pathogenesis of psoriasis." (PMID 27708240, 2016).
Alzheimer disease (3 papers, 2017 to 2023). A progressive, neurodegenerative disease characterized by loss of function and death of nerve cells in several areas of the brain leading to loss of cognitive function such as memory and language. "Overexpression of NRIP1 is associated with DS, cancer, inflammation, and Alzheimer disease." (PMID 33869171, 2021). "It was also reported that NRIP1 was involved in Alzheimer disease pathology, and the levels of NRIP1 were reduced in Alzheimer disease postmortem brains." (PMID 33869171, 2021). "It is an interesting question whether the NRIP1 mRNA m6A modification is also involved in Alzheimer disease." (PMID 33869171, 2021).
chronic lymphocytic leukemia (3 papers, 2015 to 2024). "Most recently, low level of NRIP1 has been demonstrated as a marker of poor prognosis in chronic lymphocytic leukemia patients." (PMID 26213846, 2015).
heart failure (3 papers, 2023 to 2025). Inability of the heart to pump blood at an adequate rate to meet tissue metabolic requirements. "Additionally, heart diseases, such as heart failure and myocardial infarction, may be regulated by NRIP1." (PMID 37026010, 2023).
ovarian carcinoma (3 papers, 2019 to 2022). A malignant neoplasm originating from the surface ovarian epithelium. "Studies have also verified that CircRNA NRIP1 is up-regulated in paclitaxel resistant ovarian cancer tissues and cells and knockdown of CircRNA NRIP1 restrains the drug resistance via sponging miR-211-5p." (PMID 34689819, 2021). "We treated ovarian cancer cell lines with OSU-ERb-12 and determined the ERα protein level and expression of two ERα target genes, CCND1 and NRIP1." (PMID 35565440, 2022).
coronary artery disease (2 papers, 2021 to 2022). "MiR-376a-3p, proposed as a biomarker of coronary artery disease, acts by nuclear receptor-interacting protein 1 (NRIP1) leading to the cellular apoptosis." (PMID 35897722, 2022). "In addition, miRNA-376a-3p overexpression inhibited the progression of coronary artery disease through regulating NRIP1." (PMID 33600548, 2021).
Depression (2 papers, 2017 to 2024). "In mice hippocampus, increased levels of NRIP1 expression are associated with depression-like symptoms." (PMID 28848387, 2017). "From a new perspective, the study explores the molecular interactions between stress-induced damage and cholesterol metabolism, elucidating the roles of NR3C1/NRIP1/NR1H2 in the mechanisms underlying depression-like behavior induced by short-term restraint stress." (PMID 39125645, 2024).
ductal carcinomas (2 papers, 2007 to 2015). "Indeed, NRIP1 is a target gene of microRNA-125b (miR-125b), which has been found to be underexpressed in ductal carcinomas." (PMID 26492163, 2015). "Majority of genes with this function were upregulated in ductal carcinomas such as AHCTF1, IRAK1, NRIP1, ADNP." (PMID 17389037, 2007).
endometriosis (2 papers, 2005 to 2020). The growth of functional endometrial tissue in anatomic sites outside the uterine body. "To evaluate the polygenic role of NRIP1 gene variants in human endometriosis, we decided to preliminary explore the allelic frequencies and genotypes of these mutations in women affected by endometriosis and unselected controls." (PMID 16131398, 2005). "Association studies of common DNA variants of the NRIP1 gene in relation to human endometriosis." (PMID 16131398, 2005). "Moreover, we found that Arg448Gly, a common polymorphism located within NRIP1 gene, is associated with endometriosis in a case-control study (59 cases and 141 controls, pallele positivity test = 0.027)." (PMID 16131398, 2005). "Our results suggest that NRIP1 gene variants, separately or in combinations, might act as predisposing factors for human endometriosis." (PMID 16131398, 2005). "Our results support that NRIP1 gene might contain alleles related to endometriosis in humans." (PMID 16131398, 2005). "According to previous data, mouse models reports and the present results, NRIP1 gene appears to be an attractive gene for human endometriosis etiology and other related pathologies." (PMID 16131398, 2005). "Direct inspection of genotypes in patients revealed three genotype patterns within the NRIP1 gene that appear to be over-represented in women affected by endometriosis (p = 0.006, Fisher exact test)." (PMID 16131398, 2005). "According to previous data, mouse models reports and the present results, NRIP1 appears to be an attractive candidate gene for human endometriosis etiology and other estrogen-related pathologies." (PMID 16131398, 2005). "We have sequenced the complete coding region of NRIP1 gene in 20 unrelated patients affected by endometriosis." (PMID 16131398, 2005). "Overall, our results might support the role of NRIP1 gene in endometriosis, although given the small sample size, we propose an extensive re-analysis by increasing the sample size to confirm our results." (PMID 16131398, 2005). "This last result implies that the genetic variants identified are germ-line and, consequently, somatic mutations at NRIP1 locus are not commonly involved in the pathogenesis of human endometriosis." (PMID 16131398, 2005). "Overall, our results are preliminary providingt suggestive, but not definitive, evidence of NRIP1 gene involvement in human endometriosis." (PMID 16131398, 2005).
endothelial dysfunction (2 papers, 2017 to 2020). In vascular diseases, endothelial dysfunction is a systemic pathological state of the endothelium (the inner lining of blood vessels) and can be broadly defined as an imbalance between vasodilating and vasoconstricting substances produced by (or acting on) the endothelium. "There is a possibility that upregulated NRIP1 co-activates anti-angiogenic factors to promote the endothelial dysfunction in PE." (PMID 32230784, 2020). "It is possible that upregulated NRIP1 may synergize with anti-angiogenic factors to induce the endothelial dysfunction ultimately leading to PE." (PMID 28939845, 2017).
metabolic syndrome (2 papers, 2011 to 2017). A cluster of metabolic risk factors for CARDIOVASCULAR DISEASES and TYPE 2 DIABETES MELLITUS. "Whether NRIP1 contributes to the metabolic syndrome often associated with PE or it directly regulates sFlt1 expression remains to be explored." (PMID 28939845, 2017).
osteoporosis (2 papers, 2005 to 2025). A condition of reduced bone mass, with decreased cortical thickness and a decrease in the number and size of the trabeculae of cancellous bone (but normal chemical composition), resulting in increased fracture incidence. "In addition, we have found a genetic interaction of NRIP1 gene with Estrogen receptor alpha and beta (ESR1 and ESR2) genes in two estrogen-dependent diseases such as male infertility and osteoporosis (manuscript in preparation)." (PMID 16131398, 2005).
renal carcinoma (2 papers, 2021). A carcinoma arising from the epithelium of the renal parenchyma or the renal pelvis. "Moreover, we also noticed an inhibition of circ_NRIP1 knockdown on PI3K and AKT activities, which was previously disclosed in renal carcinoma cells." (PMID 33957921, 2021).
viral infections (2 papers, 2020 to 2023). "The top 4 were “Cell matrix adhesion and organization” (COL6A1, COL6A2, COL18A1, JAM2, ADAMTS5 and POFUT2), “Immune/virus infection response” (MX1 and MX2), “Histone modification and chromatin remodeling” (NRIP1) and “Glycerolipid and lipid metabolism” (AGPAT3)." (PMID 38095646, 2023).
acute lung injury (1 paper, 2022). A condition of lung damage that is characterized by bilateral pulmonary infiltrates (pulmonary edema) rich in neutrophils, and in the absence of clinical heart failure. "Given that the activation of the NF-κB signaling pathway could be activated by NRIP1, it is likely that NRIP1 may partake in the pathogenesis of acute lung injury." (PMID 35460552, 2022). "Recently, evidence has shown that nuclear receptor interacting protein 1 (NRIP1) is involved in acute lung injury (ALI) progression, but the specific mechanism remains unclear." (PMID 35460552, 2022).
COVID-19 (1 paper, 2023). A disease caused by infection with severe acute respiratory syndrome coronavirus 2. "The results revealed various diseases from the common DEGs of AKI, CKD, and COVID-19, which include DUSP6, NRIP1, TNFAIP8, S1PR1, and TANK." (PMID 37026010, 2023).
dilatation of the ureter (1 paper, 2021). "A causative role of this variant is supported by knock-down of Nrip1 in X. laevis larvae that causes a similar CAKUT phenotype (hydroureter, hydronephrosis, and ureterocele)." (PMID 33625646, 2021). "A heterozygous truncating variant in NRIP1 recently has been identified in a large kindred with different forms of CAKUT (kidney cysts, kidney dysplasia, dilatation of the ureter, and VUR)." (PMID 33625646, 2021).
Erythema (1 paper, 2016). Redness of the skin, caused by hyperemia of the capillaries in the lower layers of the skin. "The scores of erythema and scaling, and thickness of epidermis of Nrip1−/− mice were all decreased before the 3rd day." (PMID 27708240, 2016). "On the third day, indicated by erythema and scaling, the skin inflammation of Nrip1−/− mice was weaker than WT mice." (PMID 27708240, 2016).
esophageal carcinoma (1 paper, 2020). A primary or metastatic malignant neoplasm involving the esophagus. "According to Gene Expression Profiling Interactive Analysis (GEIPA) database, level of NRIP1 was higher in tumor tissues than that in normal specimens in esophageal carcinoma." (PMID 32653032, 2020). "Besides, a negative correlation between NRIP1 and miR-140-3p was observed in esophageal carcinoma by using starBase Pan-Cancer Analysis." (PMID 32653032, 2020).
Infertility (1 paper, 2006). "Knockout mice of steroid receptor co-activator 3 (SRC-3), a member of p160 family, exhibit infertility, and those of nuclear receptor interacting protein 1 (Nrip1/RIP140) are also infertile due to the blockage of the oocytes release from the Graafian follicles by the ovulatory stimuli." (PMID 17014737, 2006). "Knockout mice of steroid receptor co-activator 3 (SRC-3), a member of p160 family, exhibit infertility, and those of nuclear receptor interacting protein 1 (Nrip1/RIP140) are also infertile due to the blockage of the oocyte release from the Graafian follicles by the ovulatory stimuli." (PMID 17014737, 2006).
liver cancer (1 paper, 2023). An epithelial or non-epithelial malignant neoplasm that arises from the liver. "From these studies, NRIP1 is implicated in the development of NAFLD/NASH due to metabolic and inflammatory dysregulation and is downregulated in HCC, stimulating anti-apoptotic signaling and acting as an enhancer of proliferation, growth, and malignant potential of liver cancer cells." (PMID 37760534, 2023).
metastatic tumor (1 paper, 2026). "These mutations were all absent in metastatic tumor samples, which presented with FIP1L1 and NRIP1 not observed in the primary tumor samples." (PMID 41614915, 2026).
papillary thyroid carcinoma (1 paper, 2021). "This study aims to clarify the roles of circRNA nuclear receptor-interacting protein 1 (NRIP1; circNRIP1) and the possible mechanisms in papillary thyroid carcinoma (PTC)." (PMID 34689819, 2021).
peripheral nerve injury (1 paper, 2026). Injury to a peripheral nerve. "Peripheral nerve injury upregulates circNrip1, but not Nrip1 mRNA, in injured DRG neurons, at least in part due to increased binding of the RNA-binding protein FUS to Nrip1 pre-RNA, thereby promoting circNrip1 formation." (PMID 41957537, 2026).
pulmonary edema (1 paper, 2022). Accumulation of fluid in the lung tissues causing disturbance of the gas exchange that may lead to respiratory failure. "Six hours after intratracheal instillation of PA, mice developed typical symptoms of pulmonary edema, manifested by decreased TLC and increased H, and mice in which NRIP1 expression was perturbed had TLC, attenuated H, and improved lung function." (PMID 35460552, 2022).
skin tumor (1 paper, 2015). "Additionally, the skin tumor in the Nrip1 deficient mouse was smaller than the skin tumors found in the wildtype mice." (PMID 26492163, 2015). "However, with the exception of one skin tumor, no malignancies were found among the nine Nrip1 deficient females." (PMID 26492163, 2015).